SDHB (succinate dehydrogenase complex iron sulfur subunit B)
Diseases named in the same sentence as SDHB in open-access papers (continued):
Sharing a sentence is not in itself a finding about the gene and the disease.
head and neck squamous cell carcinoma (2 papers, 2015 to 2022). A squamous cell carcinoma that arises from any of the following anatomic sites: lip and oral cavity, nasal cavity, paranasal sinuses, pharynx, larynx, and salivary glands. "Likewise, circulating levels of succinate were higher in patients with head and neck squamous cell carcinoma, and in Cowden Syndrome patients with germline mutations of phosphatase and tensin homolog (PTEN), SDHB or SDHD, than in the healthy controls." (PMID 36551845, 2022). "Circulating succinate was elevated in patients with head and neck squamous cell carcinoma, along with increased expression of SUCNR1, HIF1α, SDHA and SDHB in the tumor tissue relative to matched normal mucosa, further highlighting a role of succinate as oncometabolite." (PMID 36551845, 2022).
hemangioblastoma (2 papers, 2019 to 2020). "The lack of established mechanisms for these cancers is highlighted specifically in the study attributing SDHB mutation to hemangioblastoma." (PMID 33153035, 2020). "Overall, there are few cases of hemangioblastoma, with only 19 of the total 35 patients testing positive for SDHB mutation." (PMID 33153035, 2020). "Among the 90 cases of CNS tumors, only three cases of hemangioblastoma showed loss of SDHB immunoexpression." (PMID 30971719, 2019). "In the present study, we performed SDHB immunohistochemistry in various types of CNS tumors and found a significant proportion of hemangioblastomas with loss of SDHB immunoexpression." (PMID 30971719, 2019). "However, to elucidate the association between SDHB inactivation and hemangioblastoma, further comprehensive molecular analyses, including epigenetic analyses, should be conducted." (PMID 30971719, 2019). "Therefore, to elucidate the mechanism involved in the loss of SDHB immunoexpression in hemangioblastoma, further comprehensive molecular genetic analyses of SDHx mutations, including promoter methylation and/or VHL testing, should be performed." (PMID 30971719, 2019). "To examine SDHB immunoexpression in hemangioblastoma, we performed SDHB immunohistochemistry in 35 hemangioblastoma cases with two different primary antibodies against SDHB." (PMID 30971719, 2019). "In our study, we included two cases of hemangioblastoma associated with VHL disease and observed a weak-diffuse pattern of SDHB immunoexpression." (PMID 30971719, 2019). "In the present study, we initially observed a weak-diffuse pattern of SDHB in 19 cases (54.3%) of hemangioblastoma." (PMID 30971719, 2019). "Unexpectedly, we found SDHB immunonegativity in hemangioblastoma." (PMID 30971719, 2019). "We further investigated SDHB immunoexpression in 35 cases of hemangioblastoma and found that 28 (80%) showed either negative or weak-diffuse pattern of SDHB immunoexpression, which suggests the inactivation of SDH." (PMID 30971719, 2019).
hepatoblastoma (2 papers, 2023 to 2025). Hepatoblastoma (HB) is a malignant hepatic tumor and is the most common pediatric liver cancer. "Additionally, the metabolic dysregulation caused by altered SDHB function, such as in hepatoblastoma, can be targeted to inhibit tumor cell proliferation." (PMID 40724918, 2025).
hypertrophic cardiomyopathy (2 papers, 2021 to 2023). A condition in which the myocardium is hypertrophied without an obvious cause. "This includes, on the rarer end of the phenotypic spectrum, hypertrophic cardiomyopathy, which is observed in individuals with biallelic variants in DLD, SDHA, SDHB, and SDHD." (PMID 38031187, 2023). "In our study, SDHB carriers had no metastasis; only one case had hypertrophic cardiomyopathy, additively (Case 15)." (PMID 33777662, 2021).
oligodendroglioma (2 papers, 2018 to 2019). A well-differentiated (WHO grade II), diffusely infiltrating neuroglial tumor, typically located in the cerebral hemispheres. "Moreover, the underexpression of SDHB may contribute to the epigenetic reprogramming of oligodendrogliomas via the same pathomechanism as triggered by the IDH-mutation." (PMID 29890994, 2018). "In the present study, we performed SDHB immunohistochemistry on various types of CNS tumors and observed that all cases of oligodendroglioma (9 cases) and meningioma (10 cases) showed strong granular immunopositivity." (PMID 30971719, 2019). "Many of these candidates (e.g. ELTD1, SDHB, SEPW1, SLC17A7, SZRD1, THAP3, ZBTB17) are likely to push, whereas others (e.g. CAP1, HBXIP, KLK6, PARK7, PTAFR) might counteract oligodendroglioma development." (PMID 29890994, 2018). "Interestingly, several of these genes (e.g. ELTD1, SDHB, SEPW1, SLC17A7, SZRD1, THAP3, ZBTB17) are likely to push, whereas other genes (e.g. CAP1, HBXIP, KLK6, PARK7, PTAFR) might restrict oligodendroglioma development." (PMID 29890994, 2018).
omphalocele (2 papers, 2023 to 2025). Omphalocele is an embryopathy classified in the group of abdominal celosomias and is characterized by a large hernia of the abdominal wall, centered on the umbilical cord, in which the protruding viscera are protected by a sac. "Although omphalocele is not commonly linked to SDHB mutations in the literature, the presence of an omphalocele on prenatal ultrasound suggests that the c.725G>A (p.R242H) mutation might contribute to its development." (PMID 40150018, 2025). "One case of prenatal ultrasound revealed omphalocele, an absence of the left limb, and WES revealed the SDHB gene in proband c." (PMID 37726736, 2023).
prostate adenocarcinoma (2 papers, 2020 to 2021). "Unlike previous studies on prostate adenocarcinoma cells, SDHB protein levels and activity were relatively unchanged in Clpx−/− and Clpp−/− MEL cells." (PMID 34280433, 2021).
Renal oncocytoma (2 papers, 2017 to 2022). "Renal oncocytoma was described as part of three cases of RAPTAS (two with an SDHB mutation and one with a MAX mutation)." (PMID 28973655, 2017). "Negative immunostaining for SDHB in the daughter’s tumor and the same variant identified through blood samples changed the diagnosis of renal oncocytoma to SDHB-deficient RCC." (PMID 35869040, 2022). "Twenty-six years prior, her daughter, who was 25 years old at the time, had undergone radical nephrectomy for a pathologic diagnosis of renal oncocytoma of the right kidney; SDHB immunostaining of her daughter’s tumor was also negative retrospectively." (PMID 35869040, 2022).
viral infection (2 papers, 2019 to 2021). "The virus infection significantly increased the expression of subunit SDHB (succinate dehydrogenase) and MTCO1 (cytochrome c oxidase subunit I), critical components of RC complexes II and IV, respectively." (PMID 31011285, 2019). "However, the increased expression of TFAM corroborated well with our findings that virus infection enhanced the expression of SDHB and MTCO1, components in mitochondrial RC complexes." (PMID 31011285, 2019).
-deficient (1 paper, 2018). "Succinate dehydrogenase-deficient RCC is rare and results from inherited germline mutations in the succinate dehydrogenase (SDH) gene, most commonly SDHB but also in SDHA, SDHC and SDHD." (PMID 30123932, 2018).
acne (1 paper, 2020). An inflammatory process of the sebaceous glands which is characterized by comedones, nodules, papules and/or pustules on the skin. "Case report: We describe the case of a 19-year-old Caucasian man with a germline SDHB mutation, who presented with acne vulgaris resistant to medical treatment." (PMID 33113876, 2020).
adenoma (1 paper, 2017). A neoplasm arising from the epithelium. "Immunostaining with SDHA and SDHB antibodies is a valuable diagnostic tool to screen adenomas prior to requesting genetic analysis." (PMID 28284009, 2017).
bowel cancer (1 paper, 2021). "While the germline alterations in certain susceptibility genes were also detected in the bowel cancer samples including FANCD2, CDH1, FLCN, MEN1, SDHB, and SLX4, which have been rarely reported in the Chinese population." (PMID 35154239, 2021).
breast adenocarcinoma (1 paper, 2024). "This study compares metabolic adaptations between the SDHB KO human breast adenocarcinoma cell line MDA231 and SDHB KO MDA231 cells in which SDHA was silenced, resulting in the absence of CII-low." (PMID 39335562, 2024).
cholangiocarcinoma (1 paper, 2025). A carcinoma that arises from the intrahepatic biliary tree (intrahepatic cholangiocarcinoma) or from the junction, or adjacent to the junction, of the right and left hepatic ducts (hilar cholangiocarcinoma). "This case underscores the imaging similarities between PHL and cholangiocarcinoma, and for the first time, it highlights the significance of SDHB positive expression in PHL." (PMID 41333221, 2025).
chromophobe renal cell carcinoma (1 paper, 2012). Chromophobe renal cell carcinoma is a rare subtype of renal cell carcinoma, originating from the intercalating cells of the collecting ducts and macroscopically manifesting as a well-circumscribed, highly lobulated, solid tumor that is usually diagnosed at an early stage. "VHL and SDHB mutations were investigated using genomic DNA extracted from paraffin-embedded tumor sections (both from the seminal vesicle tumor and from the chromophobe renal cell carcinoma)." (PMID 22344361, 2012).
co-infection (1 paper, 2020). "However, the fitness defect observed for the sdhB mutant strain during co-infection with frdA mutant strain, suggests that succinate oxidation is conditionally beneficial to infection when functional FRD is present." (PMID 32106241, 2020).
Cowden-3 syndrome (1 paper, 2022). "Mutations in the SDHB and SDHD genes have been reported to be associated with the so-called Cowden-2 syndrome (CS-2) and Cowden-3 syndrome (CS-3)." (PMID 36553592, 2022).
cystitis (1 paper, 2015). Inflammation of the urinary bladder. "While both E. coli and P. mirabilis required TCA cycle reactions for fitness in vivo, sdhB was required for fitness only during cystitis (bladder CFU) in E. coli and only during pyelonephritis (kidney CFU) in P. mirabilis (P>0.050)." (PMID 25568946, 2015).
developmental delay (1 paper, 2020). "The final pathogenic SDHB variant reported in the mitochondrial disease literature was identified in a 12 month old child who presented with developmental delay and truncal hypotonia (Case 43)." (PMID 33162331, 2020). "The patient was an 18-month child who presented with developmental delay, hypotonia and ataxia, who was subsequently found to harbour a homozygous c.304G>A p.(Ala102Thr) SDHB variant." (PMID 33162331, 2020).
diabetic cardiomyopathy (1 paper, 2025). Diabetic cardiomyopathy is a disorder of the heart muscle in people with diabetes. "Notably, GSTK1 and UGT2B subfamily members co-regulate Chemical carcinogenesis-DNA adducts, Drug metabolism-Cytochrome P450, and extracellular exosome signaling, while IDH1/SDHB/SDHD link TCA cycle defects to redox imbalance in diabetic cardiomyopathy and tumorigenesis." (PMID 40626307, 2025).
emphysema (1 paper, 2022). "Moreover, SDHB levels were higher in emphysema patients compared to nonsmokers." (PMID 35884802, 2022).
endometrial cancer (1 paper, 2022). Primary or metastatic malignant neoplasm involving the endometrium (mucous membrane that lines the endometrial cavity). "Melatonin inhibits endometrial cancer progression by inhibiting succinate accumulation induced by the estrogen/UBC/SDHB signaling pathway." (PMID 35263200, 2022).
gastric adenocarcinoma (1 paper, 2021). "GTT decreases the levels of the NDUFB8 subunit of complex I and SDHB subunit of complex II of the mitochondrial electron transfer chain, inhibits oxidative phosphorylation, increases generation of reactive oxygen species, and induces apoptosis in gastric adenocarcinoma cells." (PMID 34884479, 2021).
Graves disease (1 paper, 2019). Graves' disease is an autoimmune disorder that leads to overactivity of the thyroid gland (hyperthyroidism).It is caused by an abnormal immune system response that causes the thyroid gland to produce too much thyroid hormones. "Our case illustrates, to the best of our knowledge, the first reported primary PGL of the tongue with a documented mutation in SDHB gene, in a patient with asymptomatic Graves’ disease." (PMID 30997073, 2019).
hand and foot syndrome (1 paper, 2020). "The second patient carried an SDHB germline mutation and was treated with antibiotics for severe hand and foot syndrome that was complicated by an infection with Pseudomona aeruginosa." (PMID 32824391, 2020).
head and neck cancer (1 paper, 2022). A primary or metastatic malignant neoplasm affecting the head and neck. "Recent studies described the germline variants of CDKN2A, RECQL4, and SDHB in the DNA repair genes associated with a high risk of head and neck cancer in young patients." (PMID 36552033, 2022).
hepatic leiomyosarcoma (1 paper, 2025). "However, the expression pattern and clinical significance of SDHB in soft tissue sarcomas, especially in primary hepatic leiomyosarcoma (PHL), remain inadequately explored." (PMID 41333221, 2025).
hereditary cancer syndrome (1 paper, 2024). "Overall, 86 (36.4%) of the 236 patients who received genetic testing results tested positive for an LPV/PV in a hereditary cancer syndrome gene; one patient tested positive for two LPV/PVs (SDHB and CHEK2), resulting in a total of 87 LPV/PVs identified." (PMID 39539798, 2024).
ileal neuroendocrine tumors (1 paper, 2012). "However, data on the prevalence and the clinical implications of SDHB immunoreactivity in ileal neuroendocrine tumors are still lacking." (PMID 24213468, 2012).
iron deficiency (1 paper, 2022). "In mammals, ACO2, NDUF8, and SDHB are downregulated in conditions of iron deficiency, but the mechanisms causing this decrease are not the same for all of them." (PMID 35038030, 2022).
leukodystrophy (1 paper, 2020). Leukodystrophies are a group of rare, progressive, metabolic, genetic diseases that affect the brain, spinal cord and often the peripheral nerves. "Other mutations of SDH subunits that have been implicated in neurodegenerative diseases include SDHA causing ataxia and SDHA, SDHB, SDHD, and SDHAF1 leading to leukodystrophy, yet these studies have been limited to few patients." (PMID 33153035, 2020).
Leukoencephalopathy (1 paper, 2020). This term describes abnormality of the white matter of the cerebrum resulting from damage to the myelin sheaths of nerve cells. "One patient (Case 40) who presented with loss of motor skills secondary to leukoencephalopathy was found to harbour a c.143A>T p.(Asp48Val) SDHB variant in trans with a c.689G>A p.(Arg230His) SDHB variant." (PMID 33162331, 2020).
liver fibrosis (1 paper, 2025). "Here they show that mitochondria-localized NEK7 couples mitochondrial complex II subunit SDHB to maintain the homeostasis of electron transport in hepatocytes, thereby impeding the progression of liver fibrosis." (PMID 41315267, 2025).
major depressive disorder (1 paper, 2024). An episode of depression lasting two or more weeks without an intervening episode of mania. "In the TCA cycle, CS, IDH3G, SDHA, and SDHB were upregulated in major depressive disorder and downregulated in ketosis, whereas SUCLG2 was downregulated in both." (PMID 39125835, 2024).
malaria (1 paper, 2020). Malaria is a serious and sometimes fatal disease caused by a parasite that commonly infects a certain type of mosquito which feeds on humans. "All human proteins in this cluster were known to be drug targets and there were 19 associations of these five human proteins (SUCLG1, SDHA, SDHB, SDHC, and SDHD) and five malaria proteins (PVX_096130, PVX_123265, PVX_003675, PVX_113540, and PVX_003575)." (PMID 32075230, 2020).
meningioma (1 paper, 2019). A generally slow growing tumor attached to the dura mater. "A case of atypical meningioma was reported in a patient with a germline mutation in the SDHB gene and molecular analyses with tumor tissue confirmed an SDHB mutation in the meningioma." (PMID 30971719, 2019).
nasopharyngeal carcinoma (1 paper, 2025). A carcinoma arising from the nasopharyngeal epithelium. "By contrast, patients with low SDHB expression presented a significantly shorter OS than those with high SDHB expression in nasopharyngeal carcinoma." (PMID 40563592, 2025).
neurofibromatosis syndrome (1 paper, 2022). "Two nonsyndromic patients (cases 1 and 2) were negative to germline mutations in genes VHL, SDHB, SDHC, SDHD, SDHAF2, TMEM127, and MAX, while the third case (case 3) had clinical diagnosis of neurofibromatosis syndrome." (PMID 36187102, 2022).
non-Hodgkin lymphoma (1 paper, 2014). Distinct from Hodgkin lymphoma both morphologically and biologically, non-Hodgkin lymphoma (NHL) is characterized by the absence of Reed-Sternberg cells, can occur at any age, and usually presents as a localized or generalized lymphadenopathy associated with fever and weight loss. "Furthermore, mRNA expression of SDHB is decreased in recovering Ramos cells in childhood non-Hodgkin lymphoma (NHL)." (PMID 25491408, 2014).
nonalcoholic fatty liver disease (1 paper, 2023). "Six of the key metagenes—INSR, MAP3K5, NDUFB8, NDUFS1, SDHB, and UQCRC2—are involved in nonalcoholic fatty liver disease (hsa04932), which is caused by a defect in insulin suppression of free fatty acid (FAA) disposal due to the induction of insulin resistance." (PMID 36979367, 2023).
oral cancer (1 paper, 2023). "Cancer and normal regions in tissue sections from oral cancer patients were delineated by a board-certified pathologist, and comparisons of SDHA and succinate dehydrogenase subunit B (SDHB) levels in each region were determined." (PMID 37945749, 2023).
oral squamous cell carcinoma (1 paper, 2023). "As one of the subunits of mitochondrial respiratory chain complex II, SDHB has been shown to significantly increase the carcinogenesis of oral squamous cell carcinoma." (PMID 36675163, 2023).
pancreatic cancer (1 paper, 2022). "The lack of SDHB function promotes the occurrence and development of several cancers, including liver and pancreatic cancer." (PMID 36185199, 2022).
pancreatic disease (1 paper, 2019). "Thus, the expression of SDHB was examined in pancreatic tissues of CP patients and compared to pancreatic tissue sections from individuals who did not die from any pancreatic disease (control tissue)." (PMID 31877753, 2019).
pediatric cancer (1 paper, 2020).
peritonitis (1 paper, 2025). Inflammation of the peritoneum (tissue that lines the abdominal wall and covers most of the organs in the abdomen). "IKZF1 exacerbates macrophage inflammation in CLP-induced peritonitis by epigenetically silencing SDHB via HDAC3-mediated deacetylation, thereby disrupting mitochondrial metabolism and amplifying pro-inflammatory signals." (PMID 41019036, 2025).
prostate acinar adenocarcinoma (1 paper, 2026). "A biopsy of the right renal lesion confirmed metastatic prostate acinar adenocarcinoma, with immunohistochemistry showing PSA (+), Ki67 (40%, indicating high proliferative activity), and succinate dehydrogenase subunit B (SDHB) (+)." (PMID 42292172, 2026).
pulmonary hamartomas (1 paper, 2024). "For one female patient with a history of paraganglioma, pulmonary hamartomas, and SDH-deficient GIST (as determined by SDHB loss in the immunohistochemistry analysis), and no detectable germline variant, somatic methylation analysis detected biallelic hypermethylation of the SDHC promoter." (PMID 39594770, 2024).
sarcopenia (1 paper, 2023). Progressive decline in muscle mass due to aging which results in decreased functional capacity of muscles. "Using this semi-quantitative method, the authors reported lower levels of the mitochondrial proteins ATP5A, NDUFS3, and SDHB in participants with frailty and sarcopenia." (PMID 36710345, 2023).